IL6 (interleukin 6)
Diseases named in the same sentence as IL6 in open-access papers (continued):
Sharing a sentence is not in itself a finding about the gene and the disease.
autoimmune disease (continued). "The excessive release of IL-6 correlates with the activation of T helper cells and the inhibition of regulatory T cells, which may support an inflammatory response or autoimmune diseases after transplantation." (PMID 37628892, 2023). "Although IL-6 plays an important role in the development and progression of inflammatory responses, autoimmune diseases, and cancers, as it can induce tissue damage, inflammation, and cell proliferation, IL-6 appears to only act on wound repair and ciliary function in CRSwNP." (PMID 37047067, 2023). "However, dysregulated, continuous IL-6 and TNFα production is involved in various health diseases, such as autoimmune diseases, cancers and muscle wasting." (PMID 36830664, 2023). "To date, no medical therapy has proven unequivocal benefit concerning clinical outcomes of PSC, but dysregulation in the JAK-STAT pathway is considered an important step in the pathogenesis of several inflammatory and autoimmune diseases with a prominent IL-6, IFN gamma, and IL-17A signature." (PMID 37256725, 2023). "Furthermore, IL-6 was linked to the suppression of T cell proliferation and prevention of neutrophil apoptosis, but also to autoimmune diseases in the case of disturbed IL-6 balance." (PMID 37626914, 2023). "The role of IL-6 in the development of many autoimmune diseases is well-known." (PMID 37894997, 2023). "Reductions in cytokines like IL-1β, IL-6, IL-12, and IL-17 caused by BTK inhibitiors in some primary autoimmune diseases may suggests possible mechanism to abrogate iRAEs." (PMID 37081866, 2023). "Interleukin-6 (IL-6) is a pleiotropic cytokine that plays a crucial role in maintaining normal homeostatic processes under the pathogenesis of various inflammatory and autoimmune diseases." (PMID 37759507, 2023). "In human autoimmune disease models, overproduction of the IL-6 and TNF-α cytokines has been linked to develop spontaneous autoimmune diseases; this might be due to their potential to reduce the suppressive activity of Tregs." (PMID 37505830, 2023). "Th17 cells generated in vitro in stimulation with TGF-β and IL-6 were reported to be non-pathogenic due to their incapability to provoke autoimmune disease after transferring into mice." (PMID 37280225, 2023). "A cytokine storm, which is an abnormally elevated level of inflammatory cytokines, such as tumor necrosis factor (TNF)-α and interleukin (IL)-6, by the innate immune system, is frequently accompanied by acute hyperinflammation in patients with infectious diseases and autoimmune diseases." (PMID 37108210, 2023). "Since IL-6 participates in the pathogenesis of inflammatory and autoimmune diseases by downregulating Treg, we studied whether IL-6 plays a role in the alteration of Treg in the absence of HCA2." (PMID 36891315, 2023). "In contrast, this also suggests that IL-6 could potentially worsen the clinical state of Th2-autoimmune diseases, such as RA." (PMID 35265152, 2022). "IL-6 is a pleiotropic proinflammatory cytokine produced by various types of cells as a result of on-going infection, trauma and immunologic challenges including autoimmune diseases." (PMID 35886067, 2022). "In the development of autoimmune diseases in PLWH, several interleukin (IL) seem involved, such as IL-6 which serum levels are found higher in people with autoimmune disorders and might be used as early predictor of this kind of diseases." (PMID 36136821, 2022). "IL-6 is a pro-inflammatory cytokine that plays a role in autoimmune disease progression." (PMID 35725652, 2022). "IL-17RB, IL-23a, IL-21, and IL-6 are significantly related to autoimmune diseases." (PMID 35358276, 2022). "Curcumin and Curcuma longa Extract may regulate inflammatory cells (such as Treg) and inflammatory factors (such as CRP, ESR, TNF-α, TGF-β1, IL-6 level), which may be its mechanism for treating autoimmune diseases." (PMID 35979355, 2022).
autoimmune disease (continued). "MAPKs can positively regulate the production of inflammatory mediators such as tumor necrosis factor, interleukin-1β, and IL-6, and their impact in T cell development and activation have also been well reported, implicating MAPKs can play a role in the pathogenesis of autoimmune disease." (PMID 36309313, 2022). "On further adjusted analyses, stratified by the level of expression of specific cytokines in autoimmune diseases, 30-day mortality was reduced in those autoimmune diseases with overexpression of IL-1, IL-6, IL-12, IFN-γ, and TNF-α, as well as in those with reduced expression of IL-4 and IL-10." (PMID 35271683, 2022). "Several IL-6 or IL-6 receptor-blocking antibodies have demonstrated promising results in (pre-) clinical studies for the treatment of cancers, chronic inflammation, and autoimmune diseases." (PMID 36248849, 2022). "Furthermore, the differentiation of Th17 cells can be completely blocked by IL-6 neutralizing antibody, and IL-6 neutralizing antibody can also inhibit the occurrence and development of autoimmune diseases mediated by Th17 cells." (PMID 35615531, 2022). "Cytokines such as tumor necrosis factor alpha (TNFα), interleukin-1 (IL-1β) and interleukin-6 (IL-6) are pro-inflammatory and play central role in inflammation of which IL-6 is the most important in chronic inflammatory and autoimmune diseases, cytokine storm and cancer." (PMID 35487926, 2022). "Interestingly though, the enriched target genes showed co-expression in the mature CD19+ B cell subset and some of them (IL-6, IL-13, PRDM1 and TLR4) have been reported to be associated genetically with autoimmune diseases." (PMID 33897713, 2021). "Recently we reported the involvement of Notch signaling and its downstream impact on IL-6 and MCL-1 in macrophages immune response and defense mechanisms against MAP infection, the bacteria that have been associated with many autoimmune diseases like RA and CD." (PMID 34025650, 2021). "IL-6 may also promote autoimmune disease by increasing the expression of cell adhesion molecules and increasing the recruitment of immune cells into tissues." (PMID 34696354, 2021). "However, uncontrolled trans-signaling via IL-6 contributes to the development of various autoimmune diseases." (PMID 33205383, 2021). "Interleukin-6 (IL-6) plays an important role in inflammation and autoimmune disease." (PMID 34561445, 2021). "IL-6 activity is also an important target of therapy in autoimmune diseases." (PMID 34141712, 2021). "In addition, polyphenols cause immunomodulatory effects against allergic reaction and autoimmune disease by inhibition of autoimmune T cell proliferation and downregulation of pro-inflammatory cytokines (interleukin-6 (IL-6), IL-1, interferon-γ (IFN-γ))." (PMID 33668814, 2021). "An IL-6 antagonist may effectively reduce mortality in autoimmune diseases by inhibiting cytokine storms." (PMID 33937333, 2021). "In the context of the data presented here, the reduced disease severity in autoimmune diseases could be due to drug-induced neutropenia or to decreased TNF-α/IL-6 levels from antibody treatment." (PMID 33986193, 2021). "IL-6 also promotes Th17 differentiation and inhibits Treg differentiation, suggesting targeting IL-6/IL-6R may have clinical applications in treating autoimmune disease and organ rejection." (PMID 34441950, 2021). "Tregs can contribute to the pathogenesis of autoimmune diseases by a multi-layered feed-forward loop: Autoantigens and pro-inflammatory cytokines (IL-1β, IL-6 etc.)activate effector Th cells which further aggravate self-tissue damage by the expression of IL-4, IL-6, IL-10, IL-12 and IFNγ." (PMID 34691057, 2021). "MIF is known to induce the expression of key proinflammatory genes, including IL-1, TNF, IL-6, IL-8, COX-2, and MMPs, and has been implicated in the development of many acute inflammatory and autoimmune diseases as well as chronic inflammatory metabolic disorders." (PMID 34445689, 2021).
autoimmune disease (continued). "The roles of IL-6 in inflammatory and autoimmune diseases have been widely described." (PMID 33816637, 2021). "Thus, SARS-CoV-2 infection in the respiratory tract can activate both NF-κB and STAT3 in a feedforward mechanism (IL-6 amplifier or IL-6 Amp) leading to multiple inflammatory and autoimmune diseases." (PMID 32983152, 2020). "Omega-3 fatty acids present with anti-inflammatory and immunomodulatory effects and might be potential therapeutic agents for inflammatory and autoimmune diseases through decreasing the levels of C-reactive protein, IL-6, and TNF-α." (PMID 32423112, 2020). "Likewise, LIF treatment increased the number of differentiated Treg cells by modifying the LIF/IL-6 balance and reducing the symptoms of an autoimmune disease such as multiple sclerosis." (PMID 33330727, 2020). "Soon after IL-6 was discovered as a B cell differentiation factor, a paper indicating that IL-6 may play an important role in autoimmune diseases was published." (PMID 32743515, 2020). "Even though the IL-6 role in AML is still not clear, high IL-6 levels have been definitively associated with chronic and autoimmune diseases." (PMID 32443460, 2020). "However, the high-levels of IL-6 production by macrophages are reported to have unfavorable consequences on inflammation, autoimmune diseases and other diseases." (PMID 32485858, 2020). "The role of IL-6 in chronic inflammation and autoimmune diseases is well established." (PMID 32466360, 2020). "Pharmacological manipulation of IL-6 secretion or the IL-6 trans-signaling pathway may offer us novel possibilities for the therapy of autoimmune diseases, infections, as well as new generation vaccine design." (PMID 31822925, 2020). "The dysregulation of IL-6 could therefore alter the Th17/Treg balance, leading to autoimmune diseases." (PMID 32655367, 2020). "Lactobacillus helveticus SBT2171 (LH2171) has been reported to ameliorate the development of autoimmune diseases, such as collagen-induced arthritis and experimental autoimmune encephalitis in mice and inhibit interleukin (IL)-6 production in antigen-presenting cells in vitro." (PMID 31057558, 2019). "Elevated IL‐6 has been reported in autoimmune diseases like neuromyelitis optica." (PMID 31313506, 2019). "In addition, we found a strong upregulation of interleukin-6 (IL-6) (F.C. 12.69) a cytokine involved in inflammatory and autoimmune diseases including SSc and, besides that, we found overexpression of several members of its signaling pathway." (PMID 30866419, 2019). "IL-6 levels are elevated in autoimmune diseases such as systemic lupus erythematosus (SLE) and RA." (PMID 30340504, 2018). "Anti-IL-6 therapy was initially developed for treating autoimmune diseases, but the role of IL-6 in chronic inflammation suggests that IL-6 blockade may be feasible for cancer treatment." (PMID 29546074, 2018). "IL-6 acts as a pro-inflammatory cytokine in various autoimmune diseases." (PMID 30687710, 2018). "Moreover, pro-inflammatory cytokines, such as TNF-α and IL-6, play crucial roles in the development of inflammatory diseases and are involved in the innate immunity and autoimmune diseases." (PMID 30002289, 2018). "IL-6 participates in autoimmune diseases such as hepatitis and multiple sclerosis, the secretion of which could be induced by TNF-α." (PMID 30057554, 2018). "Given that females are at higher risk of several autoimmune diseases, it is not surprising that females have a greater risk of AEs than males with the same levels of IL6 and time of observation." (PMID 29642948, 2018). "Furthermore, tocilizumab, an IL-6 receptor-neutralizing antibody, appears as a putative treatment in some cases of OCD as this molecule was always found effective in some autoimmune disorders where IL-6 is involved." (PMID 30096863, 2018). "Our findings provide further support that IRF4 could be a potential therapeutic target for autoimmune diseases such as RA where anti-IL-6 is effective." (PMID 30340504, 2018).
autoimmune disease (continued). "As our data demonstrated that BVDU could inhibit IL-6, IL-12, IL-23 and IL-1β production, which participate in many other autoimmune diseases such as type 1 diabetes, we further analyzed the therapeutic effect of BVDU on STZ-induced type 1 diabetes." (PMID 28272439, 2017). "It would be particularly interesting to study the effect of IL-6 on cytokine producing Th17 cells given literature suggesting that Th17 plays an important role in the pathogenesis of diverse group of autoimmune diseases as well inflammatory diseases and cancers, including ovarian cancer." (PMID 29163543, 2017). "In addition, IL-6 plays an important role in regulatory functions in T cells and B cells, indicating that it has important roles in the immunoregulation of autoimmune diseases and inflammatory responses." (PMID 29121878, 2017). "Moreover, the aberrant expression of IL-6 is an important factor in the development of many autoimmune diseases." (PMID 29312316, 2017). "IL-1Ra induction by IL-6 can protect mice from autoimmune disease." (PMID 28662714, 2017). "It is possible that in autoimmune diseases like RA, IL-6 may induce Tcon cells to resist Treg suppression, while TNFα acts on the other side of the equation to further prevent Tregs from suppressing Tcon cells." (PMID 27242798, 2016). "IL-6 has been reported to be upregulated in autoimmune diseases." (PMID 27035913, 2016). "Given the importance of TNF-α and IL-6 in the pathogenesis of autoimmune disease, we infer that MS might also exert a protective effect on RA and SLE." (PMID 27405597, 2016). "IL-6 and IL-23 are known to promote the differentiation of Th17 cells; the secretion of IL-17 by Th17 cells could trigger an inflammatory response and autoimmune diseases." (PMID 27453732, 2016). "Th17 cells could produce IL-17, TNF-α, and IL-6 and induce inflammation in the pathogenesis of autoimmune diseases." (PMID 27777959, 2016). "Indeed, the blockade of the IL-6/IL-6R signaling axis using tocilizumab, a humanized anti-IL-6R antibody, has become a therapeutic option to treat autoimmune diseases." (PMID 25884400, 2015). "Together with TGF-β, IL-6 could induce the development of Th17 cells, who was a key player in the pathogenesis of autoimmune diseases and protection against bacterial infections, from naïve T cells, while inhibit TGF-β induced Treg differentiation." (PMID 25826372, 2015). "Some cytokines like IL-6 that mediate many functions of the immune cells might play an important role in the pathogenesis of autoimmune diseases such as vitiligo." (PMID 26177100, 2015). "Furthermore it has been demonstrated that B cells with IL-10-secreting capabilities often possess the ability to secrete IL-6 as well, and B-cell derived IL-6 plays a prominent role in the pathogenesis of autoimmune diseases." (PMID 24551182, 2014). "During such conditions combination therapy of FTY720 combined with procedures that negate proinflammatory cytokines such as IL-6 may emerge as a broadly applicable approach to treat wider range of inflammatory and autoimmune diseases." (PMID 24846129, 2014). "It has previously been reported that some autoimmune diseases may be accompanied by an increase in IL-6 level probably related with the pathological changes in human body (e.g. tumorigenesis)." (PMID 25097512, 2014). "Together, these data indicate that soluble CRT in oligomerized form could play a pathogenic role in autoimmune diseases through induction of pro-inflammatory cytokines (e.g., TNF-α and IL-6) by macrophages via MAPK-NFκB signaling pathway." (PMID 24566135, 2014). "However, due to the IL-6 effects on immune system and inflammatory processes, IL-6 antagonism is now considered a potential therapeutic strategy even in various autoinflammatory and autoimmune disorders." (PMID 25061259, 2014).
autoimmune disease (continued). "One favored hypothesis of mechanism for corneal ulceration in patients with RA stems from an abnormal B and T cell interaction and increased cytokine production, specifically tumor necrosis factor (TNF) and interleukin-6 (IL-6), seen in autoimmune disease." (PMID 25031879, 2014). "A significant negative linear relationship between age and the effect size of marine-derived n-3 PUFAs supplementation on fasting blood level of IL-6 was observed in subjects with chronic non-autoimmune disease, indicating that the lowering effect was stronger in older subjects." (PMID 24505395, 2014). "Data from molecular structural studies, cell assays and in vivo models indicate that targeting the IL-6:gp130 axis by blockade of Site3 on IL-6 represents a favorable point of pharmaceutical intervention in autoimmune disease, and strongly support the ongoing clinical evaluation of olokizumab." (PMID 24670876, 2014). "Extrapolating this result to in vivo, we could suggest that an increase in IL-6 levels could result in the expansion of the B-1 cells observed in some autoimmune diseases." (PMID 23667522, 2013). "Therefore, modulation of IL-6 or downstream signals has become a promising strategy to control autoimmune diseases." (PMID 24155968, 2013). "IL-6 can mediate autoimmune disease and tumour growth through the IL-6/STAT-3 signalling pathway." (PMID 22641338, 2012). "Our recent research on MS disease (article in press) confirms these data, by showing that a sexual dimorphism in autoimmune diseases is the result of different pathways that regulate the Th cell network homeostasis: IL6 pathways in women and IFNγ pathways in men." (PMID 23148571, 2012). "However, it is interesting to note that they contain genes associated with disease in humans and dogs including epilepsy (KCNQ5), cancer (NPM1, FGR), and autoimmune disease (IL6)." (PMID 22022279, 2011). "Accumulating evidence indicates that IL-6 can enhance Th17 cell differentiation by promoting the sequential engagement of IL-21/IL-23 pathways and that it plays a critical role in Th17-dependent autoimmune diseases." (PMID 21801431, 2011). "The five most significant pathways were IL-6 signaling, IL-10 signaling, type I diabetes mellitus signaling (an autoimmune disease involving many of the same pro-inflammatory cytokines seen in the other top pathways), acute phase response signaling, and p38 MAPK signaling." (PMID 21777429, 2011). "Increased systemic or local IL-6 levels have been observed in various autoimmune diseases." (PMID 21031020, 2010). "IL-6 has been insinuated in the pathogenesis of several autoimmune diseases previously." (PMID 21209948, 2010). "High-level IL-6 expression in orbital fibroblasts suggests that it might influence inflammatory responses relevant to autoimmune disease affecting the tissues surrounding the eye." (PMID 21209948, 2010). "Elevated IL-6 levels have been observed in various autoimmune diseases, including uveitis." (PMID 21031020, 2010). "The recent availability of IL-6 blocking agents in autoimmune diseases may help promote relevant research in this area and there is increasing need to test whether inflammation blockers lessen vascular risk, or otherwise, in a range of differing populations." (PMID 19554082, 2009). "While IL-6 plays a pathogenic role in experimental-induced autoimmune disease, its function following viral-induced autoimmunity is not reprised." (PMID 19587788, 2009). "Moreover, several authors have suggested a link between childhood trauma and a possible increase in proinflammatory cytokines, such as interleukin 6 (IL-6), TNF-α, and C-reactive protein (CRP), which are known to be associated with autoimmune diseases and chronic inflammatory diseases." (PMID 40837576, 2025).